RNU4ATAC11P (RNA, U4atac small nuclear 11, pseudogene)
Gene: Small nuclear RNA gene on chromosome 9 (33,868,540 to 33,868,665, forward strand). Ensembl gene ENSG00000251748.
Homologues: Orthologues: chimpanzee RNU4ATAC11P (100% identical). Paralogues in human: RNU4ATAC16P (83% identical), RNU4ATAC18P (81% identical), RNU4ATAC2P (79% identical).